VDR (vitamin D receptor)
Diseases named in the same sentence as VDR in open-access papers (continued):
Sharing a sentence is not in itself a finding about the gene and the disease.
asthma (continued). "Other VDR variants, such as rs2189480 (A allele) or rs4328262 (G allele), were associated with severe forms of asthma, serving as a protector and risk factor respectively." (PMID 34343413, 2021). "Two variants in VDR were associated with asthma severity, the allele A of rs2189480 (OR = 0.34; 95% CI 0.13–0.89) and the allele G of rs4328262 (OR = 3.18; 95% CI 1.09–9.28)." (PMID 32834827, 2020). "The most reported VDR SNV’s associated with asthma are, rs1544410 (BsmI), rs7975232 (ApaI), rs731236 (TaqI) and rs2228570 (FokI) in several populations include Brazilian." (PMID 32834827, 2020). "Once vitamin D is an important modulator of immune system response and VDR is a map to chromosome 12q, near a region linked to asthma, variants in genes from vitamin D pathway can affect asthma and atopy." (PMID 32834827, 2020). "Animal models of asthma showed that VDR-deficient asthmatic mice have significantly higher serum IgE levels, and vitamin D alongside VDR plays a role in decreasing IgE via the modulation of IL-10 secreting B cells." (PMID 32916790, 2020). "In the present work, two VDR variants were associated with severe asthma, the rs2189480 (allele A) as a protective factor and rs4328262 (allele G) as a risk factor." (PMID 32834827, 2020). "The involvement of the vitamin D receptor in asthma susceptibility was identified in linkage and fine-mapping studies." (PMID 29202803, 2017). "A recent study provided evidence of an association between the vitamin D receptor genes and asthma in adolescents with normal 25OHD levels." (PMID 28486474, 2017). "Both CYP11A1 SNPs, rs4886595 and rs4432229, are significantly associated with asthma only in individuals carrying homozygous asthma-risk alleles of rs2107301 (VDR)." (PMID 26750596, 2016). "Significant association between polymorphisms in the VDR gene with asthma have also been reported in several genetic association studies but has not been consistently replicated." (PMID 27716192, 2016). "In humans, the data supported an epistatic effect between CYP11A1 and VDR polymorphisms, diminishing the risk to develop childhood asthma." (PMID 26750596, 2016). "An epistasic effect between genetic variants in CYP11A1 and VDR is implicated in humans due to protective effects on the development of asthma." (PMID 26750596, 2016). "In this case–control study of VDR gene variants among Cypriot adolescents, we found that the TaqI homozygous minor genotype was associated with wheezing and asthma." (PMID 26346690, 2015). "Although we adjusted the associations of VDR genotypes with asthma for vitamin D status, we cannot exclude the presence of residual confounding by variables not measured with our questionnaires." (PMID 26346690, 2015). "Further studies are needed to confirm this finding in larger populations and reveal the functional mechanisms implicated in the interaction of vitamin D with asthma and VDR genotype expression." (PMID 26346690, 2015). "Two family-based association studies conducted in North America populations and two case–control studies, in Chinese Hans and Tunisian populations, showed significant association between one or more of VDR polymorphisms with asthma." (PMID 26346690, 2015). "The first was conducted among 1090 individuals including 567 asthmatic patients and among all VDR polymorphisms tested only the ApaI marker showed a significant association with asthma." (PMID 26346690, 2015). "On the other hand, three case–control studies conducted in the Chinese Han population investigating the association of genetic variants in the VDR with asthma susceptibility have led to contradictory results." (PMID 26346690, 2015). "An association between vitamin D receptor (VDR) gene polymorphisms and asthma susceptibility is reported; however, the relationship between serum vitamin D levels and asthma remains controversial." (PMID 24943330, 2014).
asthma (continued). "Multiple studies have reported significant association between polymorphisms in the VDR gene with asthma as well as a range of autoimmune conditions, although the findings between cohorts have not been uniform." (PMID 22347615, 2012). "For example, a reduced asthma phenotype occurs in VDR−/− mice while asthma severity is enhanced in vitamin D3-deficient mice and inhibited in mice treated with 1,25(OH)2D3." (PMID 23049920, 2012). "More recently, in a series of genes that were albeit weakly associated with allergy phenotypes, VDR polymorphisms were associated with both asthma and atopy." (PMID 22347615, 2012). "The association of polymorphisms in VDR with asthma was first reported in Northern American family-based studies, but initial positive results were not replicated in subsequent populations." (PMID 21810276, 2011). "VDR variants have been extensively studied in asthma, although the results have shown contradictory." (PMID 21810276, 2011). "SNPs in the genes ADAM33 (rs528557, p = 0.000019) and VDR (rs1540339, p = 0.0014), previously associated with asthma, were also associated with asthma in this dataset at a significance level of 0.0035 corrected for multiple testing." (PMID 21103062, 2010). "Genotypic and allelic association analysis of vitamin D receptor single-nucleotide polymorphisms in the Chinese asthma study." (PMID 19622139, 2009). "Haplotype analysis of the five VDR polymorphisms showed a significant association with asthma (global-p value = 0.012)." (PMID 19622139, 2009). "Our results demonstrated that VDR rs7975232 (ApaI) variant was associated with asthma susceptibility in the cohort studied." (PMID 19622139, 2009). "In summary, we identified a significant association between a genetic variant at the VDR locus and asthma in Chinese Han population." (PMID 19622139, 2009). "Taken together, these data suggested that the VDR locus harbors variants that contribute to asthma, but the orientation of the risk allele is inconsistent across populations." (PMID 19852851, 2009). "In this model, the risk of asthma increased additively with the number of G alleles (tagging the high-risk/high-expressed haplotype) at the VDR locus and with the number of T alleles (tagging the high-risk/low-producing haplotype) at the IL10 locus." (PMID 19852851, 2009). "According to the results of a meta-analysis of the relationships between allergic diseases and VDR gene polymorphisms, positive results were confirmed for the rs1544410 BsmI polymorphism in both atopic dermatitis and asthma, and the rs731236 TaqI polymorphism in atopic dermatitis." (PMID 38807972, 2024). "In a meta-analysis including 18 mixed population studies (Egypt, Turkey, Chile, China, Ireland, Greece, Tunisia, Cyprus, and the USA), the VDR FokI T allele was associated with a decrease in asthma risk in the dominant model (p = 0.016, OR = 0.77, 95%CI = 0.63-0.95, TT+CT vs. CC)." (PMID 39583968, 2024). "However, the logistic regression analysis, where the effect described for the VDR Cdx2 (rs11568820) polymorphism on the risk of developing asthma was maintained, made it possible to avoid false positive associations." (PMID 36839181, 2023). "It was demonstrated that serum 25(OH)D level, blood eosinophil or total IgE level in asthma could be related to the single nucleotide polymorphisms in VDR or VDBP gene." (PMID 37407930, 2023). "Hypothetically, low vitamin D levels in asthma and atopy may be associated with SNPs of the VDR and VDBP genes." (PMID 37407930, 2023). "The incidence, morbidity, and mortality related with asthma was influenced by several potential risk factors such as environmental factors, infancy microbial, biome influences, and genetic background, including vitamin D receptor (VDR) gene." (PMID 35433530, 2022). "The vitamin D receptor [VDR] gene is located in chromosome 12 near asthma-related genes suggesting that polymorphisms in this gene may be a good indicator of asthma occurrence." (PMID 36292755, 2022).
asthma (continued). "Genetic polymorphisms in genes including alarmin cytokines (TSLP and IL-33) type 2 cytokines (IL-4, IL-13) and other inflammatory-related proteins (HLA, ADAM33), and vitamin D receptor have been shown to enhance, or reduce, the risk and severity of asthma in individuals." (PMID 36292755, 2022). "Thus, it is necessary to update the report based on the previous results of researches to further explore the potential role of VDR genes polymorphism in childhood asthma susceptibility." (PMID 35433530, 2022). "VDR gene rs9729 C allele was found to be negatively correlated with asthma and vitamin D shortage." (PMID 34343413, 2021). "In addition, some authors showed correlation between VDR gene polymorphisms and susceptibility to asthma and atopic dermatitis." (PMID 35002805, 2021). "Similarly, VDR rs2228570 was also a risk factor for childhood asthma susceptibility in dominant (OR = 1.281, 95% CI = 1.055‐1.555, P = .012) and allele (OR = 1.591, 95% CI = 1.052‐2.405, P = .028) models in Caucasian patients." (PMID 31541492, 2020). "However, we found that VDR rs2228570 polymorphism should be considered as a potential risk factor for the progression of asthma in the Kurd ethnicity." (PMID 31541492, 2020). "Besides, the risk of asthma progression was increased in patients with the VDR rs2228570 CC and VDBP rs7041 GG genotypes (OR = 3.56, P = .0382 and OR = 2.58, P = .01, respectively)." (PMID 31541492, 2020). "Other polymorphisms have been investigated and are, in fact, associated with anincreased frequency of asthma and other allergic diseases in population studies.However, the influence of these polymorphisms on how the VDR and other genesfunction remains unclear." (PMID 30066819, 2018). "CDX2 is capable of modifying cellinteraction between VDR and VD, and it could be associated with theprevalence of asthma, and the difficulty in controlling the disease." (PMID 30066819, 2018). "An epistatic effect between CYP11A1 and VDR polymorphisms may contribute to the predisposition to childhood asthma." (PMID 26750596, 2016). "In this study we aimed a) to examine the associations of three well known genetic variants of the VDR gene with wheezing and asthma in a cohort of adolescents in Cyprus and b) to investigate the impact of these polymorphisms in asthma susceptibility in relation to vitamin D status." (PMID 26346690, 2015). "Vitamin D and VDR have been independently linked to asthma susceptibility." (PMID 26346690, 2015). "Most of these studies examined VDR polymorphisms as independent factors for asthma susceptibility." (PMID 26346690, 2015). "We investigated whether VDR variants were associated independently or in relation to vitamin D levels with asthma in Cypriot adolescents." (PMID 26346690, 2015). "The minor TaqI genotype of VDR is associated with asthma in Cypriot adolescents." (PMID 26346690, 2015). "VDR polymorphisms have been widely studied in asthma, and the results have been contradictory." (PMID 21810276, 2011). "In that study, four of the six genotyped SNPs within the VDR gene were associated with asthma." (PMID 19852851, 2009). "Genetic variants at the vitamin D receptor (VDR) locus are associated with asthma and atopy." (PMID 19852851, 2009). "Importantly, variants in the VDR gene have been susceptible in the past to raise the risk of asthma in several populations." (PMID 19622139, 2009). "This research directs an issue to test the hypothesis described in the previous association studies between VDR variants and asthma." (PMID 19622139, 2009). "In contrast to our result, their results have not demonstrated any association between VDR rs7975232 association and asthma; however, six other VDR variants widely studied were significantly overtransmitted to both asthmatic and atopic offspring (p < 0.05) in the French families." (PMID 19622139, 2009).
asthma (continued). "However, the NHS on 517 cases and 519 controls has shown evidence for association with asthma of four out of six VDR SNPs (rs7975232, rs731236, rs2239185, and rs3782905)." (PMID 19622139, 2009). "Only one SNP located in the VDR gene demonstrated evidence of association with asthma." (PMID 19852851, 2009). "This idea stemmed from the discovery that the vitamin D receptor gene was associated with asthma." (PMID 19519921, 2009). "Two groups co-reported that genetic variants within the VDR gene were associated with asthma." (PMID 19852851, 2009). "The effect of the IL10 variant on asthma seemed dependent on the VDR variant." (PMID 19852851, 2009). "In fact, since VDR is located within the region q13-26 of chromosome 12 previously linked to asthma or related phenotypes in different populations, it is considered to be one of the candidate genes of asthma." (PMID 19622139, 2009). "We previously demonstrated that genetic variants in the VDR gene are associated with asthma." (PMID 19852851, 2009). "Two of them have suggested associations among VDR polymorphisms and asthma." (PMID 19622139, 2009). "Additionally, vitamin D receptors (VDR) in airway smooth muscle cells may exacerbate asthma symptoms in individuals with a deficiency by suppressing cytokine expression." (PMID 41153538, 2025). "Since vitamin D performs its functions by binding to the VDR, point mutations in its encoding gene may affect the function of this receptor; therefore, these polymorphisms may cause predisposition to various allergic diseases, including asthma." (PMID 38339221, 2024). "Genotyping four key VDR SNPs and assessing their association with 25-hydroxyvitamin D levels, our study unveils significant associations of the studied loci with the risk of asthma—both risk-reducing and increasing effects, differently distributed between Baltic and East Asian populations." (PMID 38339221, 2024). "Additionally, there is evidence that the VDR SNP rs731236 may be associated with an increased risk of diseases such as asthma." (PMID 39201708, 2024). "Interestingly, it was different from the finding of a previous study, which gave support for that VDR gene ApaI (rs7975232) could contribute to asthma susceptibility." (PMID 35433530, 2022). "With regard to rs2228570 and rs1544410 polymorphisms, they showed that VDR rs1544410 may be significantly associated with progression of asthma in homozygous (OR = 1.462, 95% CI = 1.016‐2.105, P = .041) and allele level (OR = 1.181, 95% CI = 1.006‐1.386, P = .042) in Caucasian population." (PMID 31541492, 2020). "VDR was selectively reduced in perilesional skin, particularly in patients with asthma or head/neck involvement, suggesting early impairment of vitamin D signaling." (PMID 40649943, 2025). "Some genetic studies have confirmed the relation between VDR gene variation and some diseases including asthma and atopic conditions." (PMID 37407930, 2023). "The aim of this study was to investigate the possible association of VDR and VDBP gene single-nucleotide polymorphisms (SNP), 25-hydroxyvitamin D (25(OH)D), blood eosinophils and total IgE level in subjects with asthma in comparison with healthy individuals." (PMID 37407930, 2023). "Further studies are warranted to investigate the VDR and VDBP gene single nucleotide polymorphisms’ role in the immune system and to evaluate their relation with vitamin D level of asthma in different populations." (PMID 37407930, 2023). "The aim of this study was to investigate a single nucleotide polymorphism (SNP) of VDR, VDBP gene in asthma cases and comparison with healthy individuals and to evaluate their relation to vitamin D in asthma." (PMID 37407930, 2023). "These were in loci previously associated with asthma exacerbations (GSDMB, RAD50, HLA‐DQB1, ADAM33, VDR, and CDHR3) or moderate‐to‐severe asthma (IKZF3, TSLP, MUC5AC, C11orf30, SMAD3, and WDR36)." (PMID 35754128, 2022).
asthma (continued). "The minor TaqI genotype of VDR was related to asthma in Cypriot adolescents; it has been suggested that those with this genotype and sufficient vitamin D levels are still susceptible to asthma." (PMID 36145154, 2022). "As it was mentioned, the potential involvement of VDR in the progression of asthma has been previously investigated, although the results are controversy." (PMID 31541492, 2020). "In summary, our results explain the influence of the genetic variations in VDR and VDBP in addition to Vit D and VDBP serum concentrations on asthma susceptibility in the Kurdish population." (PMID 31541492, 2020). "Variants in and vitamin D pathway gene (VDR, CYP2R1, CYP24A1, CYP27B1, DBP) are highlighted in immunopathologies including allergies, particularly in asthma." (PMID 32834827, 2020). "VDR polymorphism may explain why some patients with extremely low 25-OH vitamin D levels are asymptomatic, and why different studies regarding vitamin D levels and asthma severity have found different results however we could not measure 1.25 dihysroxyvitamin D levels in our study." (PMID 31183282, 2019). "An interaction between asthma-associated SNPs in CYP11A1 and VDR supported the relevance of CYP11A1 and VDR predisposing to childhood asthma." (PMID 26750596, 2016). "It has been found that different gene polymorphisms of the vitamin D receptor (VDR) and vitamin D binding protein (VDBP) have variable associations with asthma." (PMID 27382613, 2014). "Besides serum vitamin D levels also polymorphisms of genes of the vitamin D pathway such as the vitamin D receptor (VDR) have been associated with asthma, yet, not all studies revealed a correlation between vitamin D pathway polymorphisms and asthma prevalence." (PMID 25071589, 2014). "Together with different serum levels of vitamin D, also VDR and VDBP variants seem to represent a risk factor for asthma." (PMID 27382613, 2014). "Two-gene models implicating functional variants in the IL10 and VDR genes as well as in the IL10 and IL1RL1 genes were associated with asthma (p < 0.0002)." (PMID 19852851, 2009). "This notion is partially in contrast with a previous study of 7 VDR SNPs in the CAMP (Childhood Asthma Management Program) study of 582 nuclear families where SNP rs7975232 (akin ApaI) in intron 8 showed a highly significant effect." (PMID 15651992, 2005). "The VDR is also a first-order positional candidate as nearly all asthma and allergy linkage studies found linkage on chromosome 12q." (PMID 15651992, 2005). "Both genetic variants in VDR and CYP24A1 have been associated with risk of asthma and atopy." (PMID 41149648, 2025). "Additionally, VDR expression was lower in patients with comorbid asthma (p = 0.036), and significantly reduced levels of OCLN (p = 0.006), CTNNB1 (p = 0.004), and FLG2 (p = 0.046) were observed in patients with total serum IgE ≥ 100 IU/mL." (PMID 40649943, 2025). "Our preliminary results confirm that three asthma susceptibility loci: 2q12.1 (IL1RL1), 6p21.32 (HLA-DQA1/B1/A2/B2), and 22q12.3 (IL2RB) each have VDR- and IKZF3-binding sites either in enhancers predicted by GeneHancer to target these genes or within these genes themselves." (PMID 38567749, 2024). "Polymorphisms in VDR or VDBP genes may affect vitamin D levels, influencing the pathogenesis of asthma and atopy." (PMID 37407930, 2023). "We hypothesized that polymorphisms in vitamin D pathway genes such as VDR and VDBP may affect vitamin D levels and influence higher IgE levels and eosinophil counts in asthma." (PMID 37407930, 2023). "Although, several studies with asthma and atopy showed that some genotypes of VDR are associated with asthma, but not with vitamin D levels." (PMID 37407930, 2023). "Previous studies let us suggest that polymorphisms in VDR and VDBP genes may be associated with changes in vitamin D levels and involved in pathological processes of asthma." (PMID 37407930, 2023).